SEL1L (SEL1L adaptor subunit of SYVN1 ubiquitin ligase)
Diseases named in the same sentence as SEL1L in open-access papers (continued):
Sharing a sentence is not in itself a finding about the gene and the disease.
pancreatic ductal adenocarcinoma (2 papers, 2016 to 2021). An infiltrating adenocarcinoma that arises from the epithelial cells of the pancreas. "MicroRNAs that regulate SEL1L expression have been observed in human pancreatic ductal adenocarcinoma and murine neural stem cells but not in human neurons." (PMID 34955743, 2021). "SEL1L is a putative tumor suppressor gene that is downregulated in a significant proportion of human pancreatic ductal adenocarcinomas (PDAC)." (PMID 27486767, 2016). "First, miR-155 has been reported to regulate SEL1L expression in pancreatic ductal adenocarcinoma cells whereas miR-183 has been shown to regulate SEL1L and to be involved in the maintenance and lineage determination of neural progenitor cells in mouse neural stem cells." (PMID 34955743, 2021).
platelet disorder (2 papers, 2026). "We first identified SEL1L through the study of Atypical Equine Thrombasthenia (AET), an autosomal recessive platelet disorder found in thoroughbred horses." (PMID 41697739, 2026).
viral infection (2 papers, 2023 to 2025). "Recent studies have also shown that STING interacts with the HRD1-SEL1L complex, and deficiencies in HRD1 or SEL1L specifically enhance STING signaling and immunity against viral infection." (PMID 40237449, 2025). "SEL1L or HRD1 deficiency in macrophages specifically amplifies STING signalling and immunity against viral infection and tumour growth." (PMID 37142791, 2023).
anaplastic gliomas (1 paper, 2020). "In anaplastic gliomas, the frequency of SEL1L+ tumour cells ranged from >25 to 70–80% as did the immunostaining intensity, with a predominant nuclear staining." (PMID 31111685, 2020). "The relationship between SEL1L protein expression and OS was analysed in a subgroup of 58 patients, including 2 pilocytic astrocytomas, 20 diffuse and 6 anaplastic gliomas, and 30 GBs." (PMID 31111685, 2020).
anaplastic meningioma (1 paper, 2015). A WHO grade III meningioma characterized by the presence of malignant morphologic features, including malignant cytology and a very high mitotic index (20 or more mitoses per ten high power fields). "As a matter of fact, SEL1L maps on the critical region 14q31.3, which typically displays LOH in atypical and, more frequently, in anaplastic meningiomas." (PMID 25948789, 2015).
B cell deficiency (1 paper, 2026). A broad classification of disorders where circulating numbers of B lymphocytes are decreased or ineffective. "The resulting SEL1L variant restores ERAD activity, and rescues perinatal lethality, B cell deficiency, and neurodevelopmental defects." (PMID 41862645, 2026).
Brain atrophy (1 paper, 2024). Partial or complete wasting (loss) of brain tissue that was once present. "Sel1L inactivation in neurons caused global brain atrophy in adult mice, particularly cerebellar and hippocampal atrophy resulting from degeneration of Purkinje neurons and hippocampal neurons." (PMID 39135735, 2024). "Interestingly, Sel1L deficiency in neurons caused global brain atrophy, particularly cerebellar and hippocampal atrophy, in adult mice." (PMID 39135735, 2024).
brain tumor (1 paper, 2015). "In this study we genotyped five genetic variants within SEL1L selected for their potential regulatory and coding functions in a series of 412 human brain tumors and 39 GBM cell lines." (PMID 25948789, 2015). "In the current study, we analyzed five genetic variants within SEL1L with potential regulatory and coding functions and their possible association with brain tumor risk, prognosis and response to therapies." (PMID 25948789, 2015).
breast carcinoma (1 paper, 2011). "Notably, in agreement with our data, a recent report includes SEL1L peptides among the proteins identified by mass spectrometry in purified Rab27b-secretory vesicles of MCF7 breast cancer cells." (PMID 21359144, 2011).
Central diabetes insipidus (1 paper, 2018). A form of diabetes insipidus related to a failure of vasopressin (AVP) release from the hypothalamus. "Further, mice with Sel1L ablation in arginine-vasopressin (AVP) neurons progressively develop polyuria and polydipsia — characteristics of diabetes insipidus, due to a maturation defect of AVP precursor, proAVP in the ER." (PMID 29457782, 2018).
cyst (1 paper, 2021). A sac-like closed membranous structure that may be empty or contain fluid or amorphous material. "Similarly to EPB41L4B, the IPMN lesions showed a heterogeneous pattern of SEL1L staining, with some parts of the cyst layer showing positive staining and some parts negative." (PMID 34069007, 2021).
glaucoma (1 paper, 2026). Increased pressure in the eyeball due to obstruction of the outflow of aqueous humor. "This study maps putative causal POAG proteins to conventional outflow pathway cells, highlighting SEL1L as a novel target for TM homeostasis and TFPI for drug repurposing, thereby providing data-driven hypotheses to facilitate precision glaucoma therapeutics." (PMID 42278218, 2026).
hereditary ataxia (1 paper, 2014). An instance of an atactic disorder that is caused by an inherited genomic modification in an individual. "Indeed, in hereditary ataxia affecting the Finnish Hound, a defect in SEL1L, a gene important in the endoplasmic reticulum associated degradation (ERAD) process that targets misfolded proteins to the UPS, causes early onset rapidly progressive Purkinje neuron loss." (PMID 24516392, 2014).
Hyperinsulinemia (1 paper, 2018). An increased concentration of insulin in the blood. "Thus, Sel1L deficiency in POMC neurons leads to age-associated adiposity accompanied by hyperleptinemia, hyperinsulinemia, and insulin resistance." (PMID 29457782, 2018).
liver cancer (1 paper, 2023). An epithelial or non-epithelial malignant neoplasm that arises from the liver. "FAM134B inhibits HCC cell autophagy and promotes the progression of liver cancer by inhibiting the expression of ER stress‐related degradation factors such as DERL2, EDEM1, SEL1L and HRD1." (PMID 37728036, 2023). "The results exhibited varying degrees of upregulation in the expression of DERL2, EDEM1, SEL1L and HRD1 in Hep3B cells of the sh‐FAM134B group when compared to the sh‐NC group (p < 0.05), indicating the effective induction of ER stress in Hep3B liver cancer cells by sh‐FAM134B." (PMID 37728036, 2023).
lymphoma (1 paper, 2024). A malignant (clonal) proliferation of B- lymphocytes or T- lymphocytes which involves the lymph nodes, bone marrow and/or extranodal sites. "Hence, the effect pathway of SEL1L, the mutation function of hyaluronidase genes, and hyaluronan expression levels need further investigation to confirm their contribution to lymphoma pathogenesis in dogs." (PMID 39176397, 2024).
malignant glioma (1 paper, 2020). A grade III or grade IV glioma arising from the central nervous system. "SEL1L is not detected in ECs of normal or quiescent tumour blood vessels, but it is strongly expressed by ECs and vascular pericytes of the proliferative tumour neo‐vasculature in malignant gliomas (microvascular proliferations and glomeruli)." (PMID 31111685, 2020).
melanoma (1 paper, 2025). A malignant, usually aggressive tumor composed of atypical, neoplastic melanocytes. "Consistent with our in vitro findings, genes associated with the ATF4 (e.g., ATF4, DDIT3, PPP1R15A and CHAC1), ATF6 (e.g., ATF6B, CALR, SEL1L, and EDEM1) and XBP1 (e.g., SSR3 and DELR1) pathways were significantly enriched in melanoma TILs compared with healthy blood T cells." (PMID 40335738, 2025).
neuroblastoma (1 paper, 2014). Neuroblastoma (NB) is the most common solid, extracranial childhood tumor. "In addition, the expression of several genes associated with growth suppression, including CDKN1A, EGR1, NRG1 and SEL1L, were also enhanced in all S(+)-ibuprofen-treated neuroblastoma cell lines." (PMID 24173829, 2014). "In addition, S(+)-ibuprofen enhanced the expression of some favorable neuroblastoma genes (EPHB6, CD44) and genes involved in growth suppression and differentiation (EGR1, EPHA2, NRG1 and SEL1L)." (PMID 24173829, 2014).
Parkinson (1 paper, 2022). "The ERAD complex formed by SEL1L and HRD1 is conserved in mammals, and is known to be related with neurodegenerative diseases such as Parkinson’s or Alzheimer’s disease." (PMID 35388108, 2022).
pilocytic astrocytoma (1 paper, 2020). Pilocytic astrocytoma is a rare subtype of low-grade glioma of the central nervous system characterized by a well circumscribed, often cystic, brain tumor with a discrete mural nodule and long, hair-like projections that extend from the neoplastic astrocytes. "As a matter of fact, the scattered SEL1L+ cells in pilocytic astrocytoma correspond to Iba‐1+ GAMs." (PMID 31111685, 2020). "In pilocytic astrocytomas, SEL1L expression was never detected with both antibodies." (PMID 31111685, 2020).
pituitary tumor (1 paper, 2018). A benign or malignant neoplasm affecting the pituitary gland. "Correspondingly, endogenous POMC processing in a mouse pituitary tumor cell line, AtT20, as demonstrated by the presence of intermediates, was attenuated in the absence of Sel1L." (PMID 29457782, 2018).
Polydipsia (1 paper, 2018). Excessive thirst manifested by excessive fluid intake. "Additionally, mice with SEL1L deficiency in arginine vasopressin (AVP) neurons were demonstrated to develop polyuria and polydipsia, suggesting the pathophysiological importance of the SEL1L/HRD1 ERAD protein quality-control machinery in health and disease." (PMID 30282948, 2018).
Progressive cerebellar ataxia (1 paper, 2023). "The analysis of early-onset progressive cerebellar ataxia in the Finnish Hound discovered a potential functional candidate gene, sel-1 suppressor of lin-12-like (SEL1L), and led to the discovery of a homozygous missense variant within a remarkably conserved protein domain." (PMID 38003185, 2023).
prostate carcinoma (1 paper, 2016). A carcinoma that arises from epithelial cells of the prostate gland. "SEL1L has been reported to play a role in cell transformation and tumor progression in human pancreatic, breast, non–small cell lung, esophageal, and prostate cancers." (PMID 27486767, 2016).
pulmonary fibrosis (1 paper, 2024). Chronic progressive interstitial lung disorder characterized by the replacement of the lung tissue by connective tissue, leading to progressive dyspnea, respiratory failure, or right heart failure. "Limitations of our study include not elucidating the specific cell type(s) in which SEL1L is apparently diminished in pulmonary fibrosis lungs; this is an area of future study in our laboratory." (PMID 38378719, 2024).
synucleinopathies (1 paper, 2017). "The top-ranking proteins closely associated with synucleinopathies, including Sel1l and Sdhc, may be involved in α-synuclein pathologies in synucleinopathies." (PMID 28771510, 2017). "Some obviously changed proteins, which were validated by western blotting and immunofluorescence staining, including Sel1l and Sdhc, may be involved in the α-synuclein pathologies of synucleinopathies." (PMID 28771510, 2017). "Here, we found that protein processing in the ER pathway was obviously altered, and Sel1l, a component of the ER stress degradation system, was significantly upregulated in the SNpc of α-synuclein transgenic mice, indicating that protein processing in the ER pathway is involved in synucleinopathies." (PMID 28771510, 2017).
thymoma (1 paper, 2021). A neoplasm arising from the epithelial cells of the thymus. "Stimulation of the thymoma cell line EL4 with Notch ligand Delta-like 4 (DLL4) induced expression of the genes involved in ERAD including Sel1l, Hrd1, Os9, and Edem1 as well as SEL1L proteins." (PMID 34240701, 2021).
tumor (15 papers, 2010 to 2025). "The interpretation of the immunostaining should take into account the dual meaning of SEL1L, as a marker associated with either tumour progression or cell differentiation." (PMID 31111685, 2020). "SEL1L immunoreactivity correlated with tumour progression and cell proliferation, conditioning poor patient survival and response to therapy." (PMID 31111685, 2020). "In colorectal cancer, SEL1L is up‐regulated in the initial phases of neoplastic transformation, suggesting a potential function in tumour initiation and progression." (PMID 31111685, 2020). "SEL1L was expressed in the cytoplasm and/or in the nucleus of tumour cells, according to the antibody used, in GAMs and myeloid cells." (PMID 31111685, 2020). "In GBs, parenchymal tumour areas enriched in Iba‐1+/CD163+ cells were also enriched in SEL1L+ cells." (PMID 31111685, 2020). "Conversely, ECs and vascular pericytes of neo‐formed proliferated tumour vessels (MVPs and glomeruli) intensely expressed SEL1L in the nucleus and cytoplasm." (PMID 31111685, 2020). "SEL1L functions depend on tumour context being either down‐modulated in breast and pancreatic cancer 11, 12, or up‐modulated in prostate, lung and cervical cancers 13, 14, 15, including metastasis." (PMID 31111685, 2020). "The constitutive SEL1L expression in GAMs hampers the evaluation of its expression from tumour cells." (PMID 31111685, 2020). "In human malignancies, SEL1L plays either an oncogenic or a tumour suppressive role according to the cellular context or the isoform predominance." (PMID 31111685, 2020). "In GBs, diffuse and variable SEL1L immunoreactivity was found roughly in 100% tumour cells in the cytoplasm and/or in the nucleus, in relation to the antibody used." (PMID 31111685, 2020). "As the frequency of GAMs is similar in LGGs and HGGs, the increased SEL1L expression in the latter can be attributed to the increased number of SEL1L+ tumour cells and to their staining intensity." (PMID 31111685, 2020). "Endothelial cells and vascular pericytes of proliferative tumour blood vessels expressed SEL1L suggesting a role in tumour neo‐vasculature." (PMID 31111685, 2020). "The suppressor of Lin-12-like (C. elegans) (SEL1L) gene (OMIM 602329) is a putative tumor suppressor gene involved in the endoplasmic reticulum (ER)-associated degradation (ERAD) pathway implicated in tumor progression." (PMID 25948789, 2015). "Sel1L, regulates self-fate decisions and enhances tumor progression was expressed over 3 fold more in Oct4/GFP cells than the Nestin/GFP cells." (PMID 24160469, 2013). "For example, there is some evidence that increased expression of the human SEL-1 ortholog, SEL1L, correlates with a decrease in tumor aggressiveness, but how this correlation relates to effects on Notch activity is not clear." (PMID 20686701, 2010). "In these areas, SEL1L+ tumour cells corresponded to Nestin+ and Sox2+ cells." (PMID 31111685, 2020). "Neurons, intermingled with tumour parenchyma or in infiltration areas, and GAMs expressed SEL1L." (PMID 31111685, 2020). "Besides tumours, SEL1L participates in normal neurogenesis and in neurodegenerative diseases." (PMID 31111685, 2020). "On the other hand, SEL1L might contribute to tumour growth and resistance to therapy." (PMID 31111685, 2020). "There is some evidence that increased expression of SEL1L, the human SEL-1 ortholog, correlates with a decrease in tumor aggressiveness, but if this correlation reflects effects on Notch activity is not clear." (PMID 20686701, 2010). "Interestingly, our RNA-seq analysis showed that multiple ERAD-related molecules, including Sel1l/Hrd1, were upregulated in the skeletal muscle of KPC tumor-bearing Xbp1fl/fl mice." (PMID 40655023, 2025).
tumor (continued). "Therefore, it is pivotal to elucidate the mechanism by which SEL1L is involved in tumor progression within a specific tumor context and the effects of changes in SEL1L expression in tumor cells on ERAD substrates or ER homeostasis to clarify the role of SEL1L in cancer pathogenesis." (PMID 29430279, 2017).
cancer (11 papers, 2011 to 2025). A tumor composed of atypical neoplastic, often pleomorphic cells that invade other tissues. "Increased expression of Sel1L associated component of ubiquitination ligase was detected in different cancer types, which was related to reduced tumour growth and prolonged overall survival." (PMID 29415493, 2018). "It has to be stressed that regulation between OS9 and Sel1L in cancer cells needs further investigation." (PMID 29415493, 2018). "Several reports have demonstrated that SEL1L protein expression varies in human tumors relative to matched normal tissues, suggesting an involvement in cancer progression." (PMID 21359144, 2011). "Furthermore, correlation between SEL1L protein levels and poor prognosis has been reported in breast carcinoma patients and other cancers." (PMID 26491226, 2015). "A UPR element SEL1L has been recently connected to the cytotoxic effects of cancer stem cells." (PMID 32309542, 2014). "Thus, while SEL1LB and –C are generated from alternatively-spliced mRNAs expressed at low levels and up-modulated in cancer cells and under ER stress, the two new soluble SEL1L forms, abundantly expressed in cancer cells, could likely originate from proteolytic cleavage of SEL1LA." (PMID 21359144, 2011). "While the role of ERAD pathway in cancer is not fully elucidated, SEL1L has been shown to be involved in cancer pathogenesis." (PMID 26491226, 2015).
infection (5 papers, 2018 to 2025). The state of being infected such as from the introduction of a foreign agent such as serum, vaccine, antigenic substance or organism. "The silencing of SEL1L during infection also stabilized the interaction between gO and ER lectin OS-9, which also indicated that gO was the substrate of ERAD." (PMID 36012666, 2022). "Interestingly, in infected wild-type cells, Herpud1, Sel1L and calreticulin underwent rapid degradation following infection in wild-type and rUbe2g2WT cells, which was blocked in both the Ube2g2−/− and rUbe2g2C89K cells with increase in synthesis over time." (PMID 37164963, 2023). "These analyses showed that depletion of DOHH, PRKRA, SEL1L, UBE2G2, and ZFP36L2 consistently decreased DENV-2 viral protein and RNA levels during infection of Huh7.5.1 cells (respectively)." (PMID 41372121, 2025). "To test if SEL1L dependent ERAD contributes to loss of ATF6-FL during infection, we next compared ATF6 processing in HEK293-FcγR cells that were treated with non-targeting or SEL1L-targeting siRNA." (PMID 34635501, 2021).
neurodegenerative disease (4 papers, 2012 to 2022). A disorder of the central nervous system characterized by gradual and progressive loss of neural tissue and neurologic function. "Our study describes the first early-onset neurodegenerative ataxia mutation in dogs, establishes an ERAD–mediated neurodegenerative disease model, and proposes SEL1L as a new candidate gene in progressive childhood ataxias." (PMID 22719266, 2012). "The pathobiological role of the E3 ubiquitin ligase HRD1 and its adaptor protein SEL1L was previously evaluated, and their importance was demonstrated in neurodegenerative diseases." (PMID 34220315, 2021).
neurodevelopmental disorder (4 papers, 2024 to 2025). A behavioral and cognitive disorder with onset during the developmental period that involves impaired or aberrant development of intellectual, motor, or social functions. "ER-associated degradation-associated neurodevelopmental disorder with onset in infancy is associated with hypomorphic variants of SEL1L and HRD1." (PMID 37943610, 2024). "In the accompanying paper, we reported 3 hypomorphic biallelic SEL1L and HRD1 variants causing a group of inherited disorders in 6 patients with ERAD-associated neurodevelopmental disorders with onset in infancy (ENDI)." (PMID 37943617, 2024).
neurological diseases (1 paper, 2021). "Thus, investigation into whether microRNAs (miRNAs) regulate SEL1L expression in neurons should be interesting because relationships between miRNAs and the development of neurological diseases such as PD have been reported in recent years." (PMID 34955743, 2021).